TNF (tumor necrosis factor)
Diseases named in the same sentence as TNF in open-access papers (continued):
Sharing a sentence is not in itself a finding about the gene and the disease.
macrophage activation syndrome (28 papers, 2014 to 2025). A complication of rheumatic disease that is caused by excessive activation and uncontrolled proliferation of T lymphocytes and well-differentiated macrophages. "Macrophage activation syndrome was also causally associated with hyperferritinemia levels, while hyperferritinemia levels were also causally associated with decreased whole blood ex vivo TNF response to endotoxin." (PMID 37674218, 2023). "Macrophage activation syndrome (MAS) was reported in several COVID-19 patients with severe respiratory failure, and the production of associated pro-inflammatory cytokines (IL-6 and TNFα) might contribute to hyper-inflammatory conditions." (PMID 32760407, 2020). "Hyperinflammation and macrophage activation syndrome (MAS) result in the overproduction of proinflammatory cytokines, such as the IL-1β, IL-6, and TNFα, as well as coagulation abnormalities, which contribute to organ failure and other fatalities." (PMID 35495698, 2022). "Macrophage activation syndrome (MAS) development, one of the characteristics of a cytokine storm, depends on inflammatory cytokines such as TNF-α and IL-6." (PMID 35466278, 2022). "Cytokine storm, defined as macrophage activation syndrome (MAS), is characterized by the release of multiple pro-inflammatory cytokines (IL-1β, IL-18, IL-6, IL-2, IL-7, TNF-α) and chemokines (CCL2, CCL3) from macrophages." (PMID 35008658, 2021). "SARS-CoV-2 increases interferon gamma, tumor necrosis factor-α, macrophage inflammatory protein-1 alpha, IL-2, IL-6, IL-7, IL-10, in patients, that show a form of secondary hemophagocytic lymphohistiocytosis or macrophage activation syndrome (sHLH/MAS)." (PMID 33494816, 2021). "Anti-TNF strategies efficiently lowered TNF-α levels with no clinical benefit, while Anakinra (IL-1 receptor antagonist) has only proved efficacious in a limited number of patients with macrophage activation syndrome." (PMID 41301736, 2025). "The cytokine profile in these studies is comparable to that reported in cytokine release syndromes, such as macrophage activation syndrome, which is characterized by increased expression of cytokines (IL6, IL7, and TNF) and inflammatory chemokines (CCL2, CCL7, CXC-10, and CXCL-11)." (PMID 35145507, 2021). "Careful observation revealed that the excessive cytokines and chemokines activated by macrophages (i.e., IL-6, IL-7, TNF-α, CCL-2/MCP-1, CCL-3/MIP-1α) were similar to results previously found in hemophagocytic lymphohistocytosis (HLH) and macrophage activation syndrome (MAS)." (PMID 32922406, 2020). "The pathophysiology of DM RP-ILD could be similar to that of macrophage activation syndrome (MAS), in which a variety of cytokines (e.g., interleukin (IL)-1, IL-6, tumor necrosis factor (TNF)-α) are involved." (PMID 30367666, 2018). "Compared with moderate cases, severe cases show markedly higher circulating levels of tumor necrosis factor-α (TNF-α), interleukin-6 (IL-6), IL-10, and the soluble form of IL-2 receptor, exhibiting features similar to those of cytokine storm syndromes, such as macrophage activation syndrome." (PMID 33644468, 2021).
oral lichen planus (28 papers, 2012 to 2024). Oral lichen planus is a chronic inflammatory oral condition of unknown aetiology characterized by T-cell-mediated chronic immune response and abnormal epithelial keratinization cycle. "Also, to our knowledge, it is the first meta-analysis that investigated the association between TNFα –308 G/A polymorphism and oral lichen planus risk." (PMID 29641751, 2018). "The TNFα –308 G/A polymorphism may be a useful genomic marker for oral lichen planus." (PMID 29641751, 2018). "This study was performed to investigate any possible relationship between − 1031(T/C) polymorphism (rs1799964) of the tumor necrosis factor α (TNF-α) gene with the risk and severity of oral lichen planus (OLP) disease among an Iranian population." (PMID 38317095, 2024). "The study by Zheng and co-workers found that P. melaninogenica can adhere to the cell surface, invade macrophages, and increase IL-1β, IL-6, and TNF-α expression in oral lichen planus." (PMID 37887710, 2023). "Increased risk of oral precancerous lesions, such as leukoplakia, oral lichen planus, and OSMF, was induced by TNF-α (−308) and IL-6 gene polymorphism." (PMID 35982996, 2022). "The degranulated mast cell, thus, releases TNF-alpha which further releases matrix metalloproteinase-9, breaking the integrity of basement membrane and increasing the chronicity of oral lichen planus." (PMID 34490052, 2021). "It was revealed that IL-6 and TNF-α can promote malignant transformation in patients with oral submucous fibrosis and with oral lichen planus." (PMID 32245251, 2020). "The present study also confirmed the expression of IL-1α, IL-6, IL-8, and TNF-α in oral leukoplakia and oral lichen planus specimens." (PMID 32245251, 2020). "We decided to evaluate the panel of four proinflammatory, NF-kappaB dependent cytokines (IL-1α, IL-6, IL-8, and TNF-α) not only in saliva, but also in tissue specimens of OSCCs and OPMDs such as oral leukoplakia and oral lichen planus." (PMID 32245251, 2020). "This study aimed to compare the effect of topical corticosteroid versus diode Laser irradiation in the treatment of oral lichen planus by investigating the serum level of TNF-α." (PMID 27957272, 2016). "This signifies that saliva can be a good alternate for serum to analyze TNF-α in oral lichen planus patients." (PMID 25861271, 2015). "According to a previous study, serum levels of TNF-α are significantly higher in patients with oral lichen planus compared to those in healthy controls." (PMID 23277861, 2012). "According to the results of the present study, there was a significant decrease in the serum levels of TGF-β and a significant increase in the serum levels of TNF-α in patients with oral lichen planus." (PMID 23277861, 2012). "Various molecular markers, including p63, HSP90, Ki-67, COX-2, TNF-α, and matrix metalloproteinases (MMPs), have shown relevance in oral lichen planus (OLP) by providing insights into its development and potential malignant progression." (PMID 39685946, 2024). "An example of T cell mediated chronic inflammatory response is oral lichen planus (OLP), in which infiltrating monocytes are recruited into oral mucosa developing a pro inflammatory M1 phenotype due to high levels of TNF-α and IFN-γ at the lesion site." (PMID 34199238, 2021). "Myeloid dendritic cells (mDCs) and plasmacytoid dendritic cells (pDCs) are involved in activating T cells and releasing cytokines (IL-12, IL-18, TNF-α, IFN-α) and chemokines in the oral mucosa in individuals with oral lichen planus." (PMID 37090715, 2023). "Similar results were also observed in CD8+ TRM cells, which showed that the CD8+ TRM cells in patients with erosive oral lichen planus displayed enhanced cytokine production, including IFN-gamma, TNF-a and IL-17." (PMID 38093320, 2023). "Therefore, it was reported that TNF-α might have a role in the pathogenesis of oral lichen planus." (PMID 23277861, 2012).
oral lichen planus (continued). "Significant changes were evident in the serum levels of TNF-α and TGF-β in patients with oral lichen planus." (PMID 23277861, 2012). "Key words:Oral lichen planus, diode laser, topical steroid, RAE score, TNF-α." (PMID 27957272, 2016). "Compared with healthy controls, the patients with oral lichen planus, oral leukoplakia, or OSMF all had elevated serum and salivary levels of TNF-α and IL-6, and the findings were supported by another research, revealing that TNF-α and IL-6 levels increased in OSMF patients." (PMID 35982996, 2022). "Moreover, expression of TNF-α was significantly higher in oral leukoplakia and oral lichen planus without dysplasia, whereas expression of IL-8 only in oral leukoplakia without dysplasia in comparison with NOM." (PMID 32245251, 2020). "The aim of this study was to quantitatively evaluate the salivary TNF-α level in oral lichen planus patients and to compare the levels of TNF-α between saliva and serum of OLP and controls." (PMID 25861271, 2015). "As there are no studies available which compare the levels of TNF-α in saliva and serum in Indian population, the present study was carried out to evaluate and compare the levels of TNF-α in saliva and serum of oral lichen planus patients." (PMID 25861271, 2015). "Concentrations of IL-6, IL-8, and TNF-α were also markedly higher in OSCC group as compared to subjects with oral leukoplakia without dysplasia (p = 0.0012, 0.0000, and 0.0492, respectively) and oral lichen planus without dysplasia (p = 0.0084, 0.0002, and 0.0212, respectively)." (PMID 32245251, 2020).
vascular dementia (28 papers, 2008 to 2026). A degenerative vascular disorder affecting the brain. "Analogous to pediatric HPHC, adult patients with normal pressure hydrocephalus and/or vascular dementia may also have elevated pro-inflammatory cytokine concentrations (TNFα) in association with white matter damage." (PMID 19117508, 2008). "The neuroprotective role of TNF-α has been demonstrated in experimental models and humans with Alzheimer’s and vascular dementia." (PMID 41465427, 2025). "Neuroinflammation-related pathways (such as IL-17 and TNF signaling) were grouped, indicating the role of immune-mediated processes in vascular dementia." (PMID 41032496, 2025). "Important pathways in vascular dementia, such as leukocyte transendothelial movement, cholesterol metabolism, IL-17 signaling, and TNF signaling, are likely to be grouped in different ways to show how they work at the molecular level." (PMID 41032496, 2025). "Inhibition of TNF-α by adalimumab, human monoclonal antibody against TNF-α, showed significant reduction of oxidative stress in experimental model of vascular dementia." (PMID 35313642, 2022). "As was reported, the mRNA expression of TNF-α, IL-6 and IL-1β was decreased in rats of the electroacupuncture group compared with the vascular dementia (VD) group." (PMID 31049031, 2019). "The 0.2 g/kg Cs-C-Q80 treatment only slightly downregulated the TNF-α and IL-1β, while 1.0 g/kg Cs-C-Q80 treatment significantly inhibited the TNF-α and IL-1β increasing (P<0.05), suggesting the involvement of the inflammation-resistant of Cs-C-Q80 treatment on vascular dementia." (PMID 30662512, 2018). "Furthermore, recent studies have shown that the genetic variation in tumor necrosis factor-α (TNF-α), IL-6, and other pro-inflammatory cytokines might increase the risk for development of vascular dementia and lacunar infarction." (PMID 23050663, 2012). "These immune-related pathways, including IL-17 signaling (p = 0.027874) and TNF signaling (p = 0.033137), both involving MMP9, demonstrated the role of neuroinflammation in the development of vascular dementia." (PMID 41032496, 2025). "Another RCT of 42 patients with vascular dementia and Fazekas scores of ≥ 2 found a trend towards reduction in WMH volume and inflammatory markers (CRP, IL-6 and tumour necrosis factor-alpha; TNFα) in the RIC group at 6 months follow-up." (PMID 39702489, 2024). "The significantly increased serum levels of IL-4 and IL-5 in the MCI/AD group correspond with findings in a previous study that reported elevated IL-4, IL-5, IL-1β, TNF-α, IFN-γ, G-CSF, and MIF-1b levels in patients with vascular dementia." (PMID 37760836, 2023). "Several papers demonstrate that EA-induced anti-inflammatory actions improve cognition and suppress neuroinflammatory factors such as TNF-α and IL-1β involved in toll-like receptor (TLR) signaling in animal models of vascular dementia." (PMID 31836020, 2019). "In another study, it was shown that the NF-κB, TNF-α, and IL-1β levels in the hippocampus were significantly increased in rats with vascular dementia that were not treated with nimodipine." (PMID 41464815, 2025).
apical periodontitis (27 papers, 2007 to 2025). "Multiple studies have investigated the polymorphisms of various ILs, including IL-1α, IL-1β, IL-6, TNF-α, IL-8, IL-10, and IL-12, and their association with the occurrence of apical periodontitis." (PMID 39723289, 2024). "The TNF-α polymorphism -308 G/A is associated with a higher susceptibility to apical periodontitis, particularly among heterozygotes (GA) and homozygotes (AA) carrying the variant A allele." (PMID 39723289, 2024). "Recent studies support that symptomatic apical periodontitis associates with changes in bacterial load and diversity, as well as host’s immune response, involving interleukin (IL)-1, IL-6, tumor necrosis factor (TNF)-α, and matrix metalloproteinase (MMP)-9, respectively." (PMID 28261746, 2017). "CH demonstrated significant microbial reduction (up to 99.5%), decreased inflammatory mediators (IL-1β, TNF-α), and enhanced tissue healing, making it a reliable choice for managing apical periodontitis." (PMID 41438829, 2025). "Several studies have confirmed the pro-inflammatory nature of periapical granulomas, noting higher levels of IL-1β, IL-6, TNF-α, and IL-17 in patients with symptomatic apical periodontitis compared to those with asymptomatic cases." (PMID 39723289, 2024). "TNF-α along with IL-1, can also play a key role in the development of apical periodontitis and periapical tissues." (PMID 38893626, 2024). "The cells more predominant in apical periodontitis are IL-1 α, TNF-α, or IL-6, which activate the osteoclasts (involved in the bone resorption or destruction) and fibroblasts." (PMID 38893626, 2024). "In the mechanism of apical periodontitis, cytokines are involved, including IL-6 and TNF-a for bone resorption, osteoclast activity, and proinflammatory cytokines." (PMID 36599453, 2023). "Among them, IL-1 and TNF-α have been shown to predominate both in the early phase of apical periodontitis and during the exacerbation, and both phases are characterized by the presence of clinical symptoms." (PMID 31011287, 2019). "Moreover, interactions between TNF-α polymorphism rs1800629 and RANKL polymorphism rs1054016 were linked to a decreased risk of developing persistent apical periodontitis following root canal treatment." (PMID 39723289, 2024). "Therefore, this study evaluated the immunoexpression of IL-1β, TNF-α, and IL-17 in apical periodontitis from type 2 diabetic patients through immunohistochemistry." (PMID 36819640, 2023). "Both Fusobacterium nucleatum and Porphyromonas gingivalis may contribute to the immunopathogenesis of apical periodontitis although their LPS presented different patterns of activation against macrophages as seen by the IL-1beta and TNF-alpha production." (PMID 38012618, 2023). "In addition, the lipopolysaccharides from Fusobacterium nucleatum triggers the synthesis of interleukin 1α and tumor necrosis factor-α and their release from macrophages, which in turn might be involved in apical periodontitis-related bone resorption." (PMID 31355071, 2019). "Within the limitations of this study, it can be concluded that the calcium silicate-based root canal dressing was effective in reducing RANKL/OPG, TNF-α, PGE-2, and TGF-β levels in apical periodontitis." (PMID 40155539, 2025). "A recent study on apical periodontitis found that FSH aggravated inflammation by enhancing the expression of IL-1 β, IL-6, TNF and Toll-like receptor 4 in human periodontal ligament cells." (PMID 35527996, 2022). "Moreover, there have been no clinical studies on periapical lesions in terms of anti-TNFα therapy, although a study did examine the effect of adalimumab on the healing of apical periodontitis in ferrets, and they found beneficial effects." (PMID 38256582, 2024).
apical periodontitis (continued). "Combined with the histological results and immunohistochemical staining of TNF-α and IL-6 in the periapical area, we proved that the passive ultrasonic irrigation and EASYDO ACTIVATOR treatments could reduce the levels of TNF-α and IL-6, thereby reducing bone destruction in apical periodontitis." (PMID 36053353, 2022).
contact dermatitis (27 papers, 2013 to 2026). An inflammatory skin condition caused by direct contact between the skin and either an irritating substance or an allergen. "Recent studies show that IL-6, IL-1, and TNF-α values are increased in the serum of patients with contact dermatitis, as well as in keratinocyte cell culture." (PMID 40141696, 2025). "Dermal infiltrated Ly6C+ monocytes not only express TNF-α but also directly express high-level CXCL2 to mobilize NTEM in contact dermatitis." (PMID 40185981, 2025). "We found that participants with skin lesions in form of contact dermatitis caused by chronic exposure to silver and silica nanoparticles had higher genes expression of inflammatory cytokines, including IL4, IL6, IL8, and TNF-α compared to control individuals." (PMID 38454025, 2024). "The pathophysiology of irritant contact dermatitis is characterized by the release of inflammatory mediators at the injured site, such as proinflammatory cytokines, tumor necrosis factor-alpha (TNF-α) and chemokines." (PMID 36678913, 2023). "They found that CA has anti-inflammatory activities in both acute and chronic contact dermatitis models through blocking of mRNA and protein synthesis of the cytokines, such as TNF-α, IL-6, and IL-1β, and neutrophil-mediated myeloperoxidase activity." (PMID 34040528, 2021). "Cutaneous inflammation was evaluated with clinical scoring, ultrasound imaging, skin thickness, histology, and analyses of selected biomarkers for contact dermatitis, IL-1β, TNF-α, CXCL10, and CXCR3." (PMID 31875186, 2019). "Phenol produces an inflammatory response with characteristic of contact dermatitis to stimulate the breakdown of keratinocytes with release of cytokines (IL-1α, TNF-α and IL-8)." (PMID 27916942, 2016). "Together with TNF-α, interleukin (IL)-6 plays a pivotal role in skin inflammation (e.g., contact dermatitis) and hypersensitivity response." (PMID 23710240, 2013). "Particularly, IL-1 and TNF-α have been implicated in many diseases including ICD, which accounts for 20–80% of all cases of contact dermatitis depending on the country." (PMID 24058364, 2013). "As shown in previous studies, C. pepo L. extract applied topically and orally in rats with contact dermatitis and chronic stress demonstrated a significant reduction in TNF-α and IL-6 levels, both systemically and locally in the skin, which was accompanied by a reduction in iNOS and COX-2." (PMID 41157100, 2025). "A mouse model of contact dermatitis showed that black garlic decreased the activation of macrophages, as well as the release of inflammatory mediators like nitric oxide II (NO), tumor necrosis factor (TNF-α), and interleukin 6 (IL-6)." (PMID 38339077, 2024). "Additionally, irritants cause IFN-γ to amass in the skin, and the cancellation of the IFN-γ function by anti-TNF-α antibodies impairs the development of irritant contact dermatitis." (PMID 36769309, 2023). "Additionally, baclofen reduced human PBMC chemotaxis towards chemokines, reduced PHA-stimulated human PBMC secretion of TNFα and ameliorated contact dermatitis in mice." (PMID 33418884, 2021). "Ginsenoside Rg5 could also suppress oxazolone-induced ear contact dermatitis swelling through reducing the mRNA expressions of cyclooxygenase-2, interleukin 1β, tumor necrosis factor (TNF)-α and interferon (IFN)-γ." (PMID 30135411, 2018). "Additionally, ginsenosides Rg3, Rf, and Rh2 have been reported to inhibit passive cutaneous anaphylaxis and contact dermatitis in a mouse model by suppressing the expressions of cyclooxygenase (COX)-2, interleukin (IL)-1β, tumor necrosis factor-α (TNF-α), and interferon-γ (IFN-γ)." (PMID 31817146, 2019).